BACH1 (BACH transcriptional regulator 1)
Diseases named in the same sentence as BACH1 in open-access papers (continued):
Sharing a sentence is not in itself a finding about the gene and the disease.
colitis (6 papers, 2018 to 2024). Inflammation of the colon. "Moreover, this inhibitory effect on colitis in Bach1-deficient mice was cancelled by co-treatment with the HO-1 inhibitor, ZnPP." (PMID 30487665, 2018). "The disease outcome observed here is highly consistent with previous reports on the role of Bach1 in promoting tissue damage and inflammation in murine models of colitis, neurodegenerative diseases, cardiovascular disease, sepsis and lupus erythematosus." (PMID 38066332, 2024). "In DSS-induced colitis, HO-1 is negatively regulated by transcription factor BTB domain and CNC homology 1 (BACH1), and mice deficient in BACH1 display elevated levels of colonic HO-1 and decreased disease activity." (PMID 39599629, 2024). "For example, BACH1 knockdown promotes M2 macrophage polarization to alleviate colitis and inhibits M2 macrophage polarization to inhibit GC metastasis." (PMID 37228820, 2023). "Acute colitis was induced in male C57BL/6 (wild-type) and homozygous BTB and CNC homolog 1 (Bach1)-deficient mice, which show high HO-1 expression in the colonic mucosa, using dextran sodium sulfate." (PMID 30487665, 2018). "In addition to decreasing disease activity index, BACH1 depletion dramatically increases HO-1 expression to exert an intestinal mucosal protective effect in a DSS-induced colitis mouse model." (PMID 37228820, 2023). "Furthermore, BACH1-deficient macrophages exhibit distinctly increased HO-1 levels and manifest the M2 macrophage marker to suppress TNBS-induced colitis." (PMID 37228820, 2023). "Besides, a deficiency in Bach1 ameliorates 2,4,6-trinitrobenzene sulfonic acid (TNBS)-induced colitis by modulating the development of macrophages and APCs." (PMID 36139853, 2022). "Bach1 knockout mice are protected against 2,4,6-trinitrobenzene sulfonic acid (TNBS)-induced colitis in which isolated peritoneal macrophages have characteristics of the M2 state (a state involved in immunosuppression and tissue repair) and exhibited a high level of HO-1 expression." (PMID 36139853, 2022).
coronary artery disease (6 papers, 2022 to 2026). "BACH1 is involved in the aggravation of various oxidative stress-related diseases, including ischemic heart disease, and whether it is related to ferroptosis remains unclear." (PMID 35733129, 2022).
diabetes (6 papers, 2020 to 2025). "Future work will be required to investigate the association of the BACH1 gene with genetic variants linked with the risk of insulin resistance, obesity, and diabetes." (PMID 38129407, 2023). "In mouse models, BACH1 deficiency confers protection against oxidative stress-induced diabetes." (PMID 32847508, 2020). "Our KEGG analysis also showed that BACH1 was correlated with metabolic diseases like diabetes and athrosclerosis." (PMID 35651942, 2022). "The development of BACH1 inhibitors may present a new therapeutic option for insulin resistance, diabetes, and related complications." (PMID 39887888, 2025). "Our findings revealed a crucial role for BACH1 in regulating insulin signaling, suggesting that BACH1 may become a promising target for the treatment of metabolic disorders such as obesity and type 2 diabetes mellitus." (PMID 38129407, 2023). "Additional work is required to determine whether the inhibitor that targets the interaction between BACH1 and PTP1B is an alternative more specific approach for the treatment of diabetes." (PMID 38129407, 2023).
Obesity (6 papers, 2017 to 2025). Accumulation of substantial excess body fat. "Moreover, in mice, BACH1 is shown to be involved in regulating oxidative stress, a factor in obesity-associated insulin resistance, while its hepatic deletion improves insulin signalling and glucose metabolism by modulating key protein interactions." (PMID 40118008, 2025). "In the present study, we observed that BACH1 expression was higher in the hepatocytes of individuals with obesity than those of lean individuals and in the livers of patients with NAFLD and diabetic mice than in normal control livers." (PMID 38129407, 2023). "BACH1 is elevated in the hepatocytes of individuals with obesity and patients with non-alcoholic fatty liver disease (NAFLD)." (PMID 38129407, 2023). "FXR1, NFKB1, and BACH1 are potent regulators of obesity-driven inflammation and metabolic dysfunction." (PMID 37698918, 2023). "This further underscores the relevance of BACH1 TF is the context of obesity." (PMID 40118008, 2025). "Notably, the expression of BACH1 was higher in the hepatocytes of subjects with obesity than in lean subjects." (PMID 38129407, 2023). "Furthermore, other clinical variances, including the inflammation status and metabolic disease status, such as obesity or type II diabetes of patients, might be of interest in future research on BACH1 or MCT1 expression." (PMID 40710214, 2025). "In vitro experiments have found that apoptosis caused by iron-dependent lipid peroxidation induced by the transcription factor BACH1 can stimulate the secretion of FGF21 and inhibit obesity in mice on a high-fat diet." (PMID 40656191, 2025). "We then detected BACH1 mRNA and protein levels in the liver tissues of HFD-induced obesity mice, ob/ob mice, and db/db diabetic mice." (PMID 38129407, 2023).
acute myeloid leukemia (5 papers, 2018 to 2025). Acute myeloid leukemia (AML) is a group of neoplasms arising from precursor cells committed to the myeloid cell-line differentiation. "By contrast, in acute myeloid leukemia cells, BACH1 promotes cell death by inhibiting HMOX1 expression." (PMID 36670112, 2023). "Bach1 also appears to increase the cytotoxicity of an anticancer drug by downregulating HO-1 expression in human primary acute myeloid leukemia (AML) cells." (PMID 30370001, 2018).
Down syndrome (5 papers, 2012 to 2025). "Bach1 dysregulation has been associated with Down syndrome (DS): Bach1 is significantly overexpressed in the fetal cortex of DS fetuses when compared to controls, whereas in another study, expression was significantly reduced in the frontal cortex of DS patients." (PMID 23020841, 2012). "Importantly, it has also been shown that Bach1 is significantly up-regulated in the brain of subjects with Down Syndrome increasing oxidative stress and favoring the onset of Alzheimer’s disease." (PMID 28790431, 2017).
leukemia (5 papers, 2019 to 2025). A malignant (clonal) hematologic disorder, involving hematopoietic stem cells and characterized by the presence of primitive or atypical myeloid or lymphoid cells in the bone marrow and the blood. "Out of the 132 early‐specific TF‐binding sites, such as motifs for Bach1/2, Maf(k), and Nfe2l2, 109 (83%) were significantly enriched in leukemias, whereas of the 115 intermediate‐ and mature‐specific TFs only 12 (10%) were significantly enriched in T‐ALLs." (PMID 32755029, 2020). "For example, miR-155 modulates the expression of NF-κB and MAFK via regulation of BACH1 (BTB and CNC homology 1, basic leucine zipper transcription factor 1) and LDOC1 (leucine zipper, downregulated in cancer 1) which is critical to malignant transformation in leukemia, breast and lung cells." (PMID 31781485, 2019).
non-alcoholic steatohepatitis (5 papers, 2014 to 2025). "Inhibition of Bach1 itself has been suggested to be of benefit in diseases such as non-alcoholic steatohepatitis and insulin resistance." (PMID 25019514, 2014).
esophageal cancer (4 papers, 2021 to 2023). A primary or metastatic malignant neoplasm involving the esophagus. "Our study will explore the interactions between SNHG8 and miR-1270 or miR-1270 and BACH1 in esophageal cancer." (PMID 35067159, 2022). "Knockdown of SNHG8 suppresses the progression of esophageal cancer by modulating the miR-1270/BACH1 axis." (PMID 35067159, 2022). "The subsequent results verified that knockdown of SNHG8 suppresses the progression of esophageal cancer by modulating the miR-1270/BACH1 axis." (PMID 35067159, 2022). "An increased expression of BACH1 was shown to be correlated with a poorer prognosis of patients with breast, pancreatic, colorectal, ovarian, and esophageal cancers as well as glioblastoma." (PMID 34339740, 2021). "BACH1 is involved in LncRNA SNHG8/miR-1270/BACH1 axis in esophageal cancer." (PMID 37228820, 2023). "Further mechanistic studies are required to elucidate the function of BACH1 in esophageal cancer." (PMID 37228820, 2023). "According to our mechanism, miR-1270 should be a tumor suppressor and BACH1 could promote cancer development in esophageal cancer, respectively." (PMID 35067159, 2022). "Especially in esophageal cancer, BACH1 was considered to be an oncogene promoting the development." (PMID 35067159, 2022). "Thus, we concluded that knockdown SNHG8 suppresses the progression of esophageal cancer by modulating the miR-1270/BACH1 axis." (PMID 35067159, 2022). "Moreover, BACH1 has been considered to promote the development of esophageal cancer." (PMID 35067159, 2022).
esophageal squamous cell carcinoma (4 papers, 2021 to 2024). Esophageal squamous cell carcinoma (ESCC) is a type of esophageal carcinoma (EC) that can affect any part of the esophagus, but is usually located in the upper or middle third. "Accordingly, BACH1 enhances ferroptosis sensitivity in many cell types, including mouse embryonic fibroblasts (MEFs), glioma cells, esophageal squamous cell carcinoma (ESCC) cells, and primary human macrophages." (PMID 39025451, 2024). "In esophageal squamous cell carcinoma, BACH1 negatively regulates the expression of SCD1 to inhibit MUFA generation, thereby inducing ferroptosis and facilitating lymph node metastasis." (PMID 38205151, 2024). "We investigated the functions of BACH1 in esophageal squamous cell carcinoma (ESCC), and our data firstly demonstrated that BACH1 contributes to ESCC metastasis and progression by EMT and angiogenesis." (PMID 33932125, 2021).
Hypertension (4 papers, 2018 to 2026). The presence of chronic increased pressure in the systemic arterial system. "A substantial number of studies have disclosed that a deficiency in BACH1 is beneficial in a wide range of disorders, including hypertension." (PMID 37371773, 2023). "Spontaneous hypertension led to an increase in the expression of Nrf2 inhibitors, such as Keap1 and Bach1 in the heart." (PMID 30223427, 2018). "URB597 administrated to rats with spontaneous hypertension decreased the expression of cardiac Nrf2, HO-1, Keap1, Bach1, and KAP1; increased expression of kinases ERK1/2 and MAPK; while p21, p62, and p38 amounts were not changed." (PMID 30223427, 2018). "MiR-155-5p regulated hypertension-induced VSMC migration by suppressing the expression of BACH1." (PMID 37371773, 2023). "The hypertension-induced upregulation of BACH1 in VSMCs was also erased by miR-155-5p transfection." (PMID 37371773, 2023). "Next, we examined whether the knockdown of BACH1 affected the proliferation and ROS production of VSMCs in hypertension." (PMID 37371773, 2023). "Importantly, the overexpression of miR-155-5p and knockdown of BACH1 had synergistic effects on the inhibition of VSMCs in hypertension." (PMID 37371773, 2023).
Insulin resistance (4 papers, 2014 to 2025). Increased resistance towards insulin, that is, diminished effectiveness of insulin in reducing blood glucose levels. "To determine the functional role of hepatic BACH1 in the insulin resistance of diabetic mice, we silenced BACH1 by administering AAV-shBach1 to selectively inhibit BACH1 in hepatocytes in db/db mice." (PMID 38129407, 2023). "Instead, HFD-fed hepatic BACH1-overexpressing mice exhibited aggravated hepatic insulin resistance and steatosis." (PMID 38129407, 2023). "Mechanistically, BACH1 directly interacted with PTP1B and IR-β in hepatocytes, and loss of hepatic BACH1 reduced the interaction between PTP1B and IR-β upon insulin stimulation in HFD-fed mice, thus improving insulin resistance and glucose metabolism." (PMID 38129407, 2023). "Together, these data demonstrated that overexpression of hepatocytic Bach1 aggravated HFD-induced hepatic insulin resistance and steatosis." (PMID 38129407, 2023). "Consistently, knockout of hepatic BACH1 in mice improved glucose tolerance and ameliorated insulin resistance compared with the control mice under HFD conditions, as indicated by the glucose tolerance test (GTT) and the insulin tolerance test (ITT)." (PMID 38129407, 2023). "The present study explored the role of BACH1 in insulin resistance in the livers of HFD-fed or db/db diabetic mice." (PMID 38129407, 2023). "We injected four-week-old male db/db mice with AAV-shBach1 or AAV-shCon to examine whether decreased BACH1 expression could reverse insulin resistance in db/db mice." (PMID 38129407, 2023). "We observed that the hepatocyte-specific deletion of BACH1 protected from HFD-induced steatosis, which may be associated with the improvement in insulin resistance in the liver." (PMID 38129407, 2023). "Moreover, BACH1 knockdown significantly ameliorated hyperglycemia and insulin resistance in the diabetic mouse models." (PMID 38129407, 2023). "Thus, BACH1-mediated aggravation of HFD-induced hepatic insulin resistance is mediated, at least in part, by PTP1B." (PMID 38129407, 2023). "BACH1 facilitated PTP1B binding to IR-β, suppressed insulin signaling, and aggravated insulin resistance in HFD-fed mice and diabetic mice." (PMID 38129407, 2023). "Hepatocyte-specific Bach1 deletion in male mice on a high-fat diet (HFD) ameliorates hyperglycemia and insulin resistance, improves glucose homeostasis, and protects against steatosis, whereas hepatic overexpression of Bach1 in male mice leads to the opposite phenotype." (PMID 38129407, 2023).
myocardial infarction (4 papers, 2020 to 2025). Gross necrosis of the myocardium, as a result of interruption of the blood supply to the area, as in coronary thrombosis. "Our findings on the muscle injury model are in clear contrast to previous reports showing reduction of myocardial infarction, spinal injury, and lung injury by the Bach1 deficiency in disease models." (PMID 32776961, 2020). "BACH1 has been found to repress the expression of ferritin, ferroportin, and HO‐1, thereby facilitating ferroptosis and aggravating acute myocardial infarction." (PMID 39887888, 2025). "This suggests that BACH1 sets a critical threshold for ferroptosis induction and may serve as a therapeutic target in treating ferroptosis-related diseases and conditions, including myocardial infarction." (PMID 40000618, 2025).
neuroblastoma (4 papers, 2011 to 2023). Neuroblastoma (NB) is the most common solid, extracranial childhood tumor. "In this work we demonstrated that SH-SY5Y neuroblastoma (NB) cell differentiation induced by all-trans retinoic acid (ATRA) increases cell sensitivity to oxidative stress through the impairment of Bach1-depedent HO-1 induction." (PMID 28790431, 2017). "Yet, the role of Maf proteins in Bach1 regulation, during neuroblastoma cell differentiation and in the response to oxidative stress is still completely unexplored." (PMID 28790431, 2017). "For the best of our knowledge, this is the first piece of evidence on the involvement of Bach1 in human neuroblastoma cell response to oxidative stress." (PMID 28790431, 2017). "Further experiment demonstrated that miR-380-5p could attenuate the neuroblastoma cell death induced by oxidative stress after CIR injury and this process was medicated by direct targeting BACH1 and facilitating NRF2, indicating that miR-380-5p played the neuroprotective role during CIR injury." (PMID 34046217, 2021).
osteoarthritis (4 papers, 2015 to 2023). A noninflammatory degenerative joint disease occurring chiefly in older persons, characterized by degeneration of the articular cartilage, hypertrophy of bone at the margins and changes in the synovial membrane. "An investigation into the effect of Bach1 ablation on osteoarthritis reveals significant protection against age-associated and surgically induced osteoarthritis." (PMID 36139853, 2022). "Another aging-associated disease osteoarthritis is also found to be related to Bach1 due to oxidative damage." (PMID 30370001, 2018). "During inflammation, the Bach1/HO-1 pathway regulates osteoclastogenesis, and Bach1 deficiency reduced the severity of osteoarthritis in mice by upregulating HO-1 expression." (PMID 30370001, 2018). "The objective of this study was to define the role of Bach1 in cartilage homeostasis and osteoarthritis (OA) development using in vitro models and Bach1-/- mice." (PMID 26458773, 2015). "Interestingly, the same study shows that the increased HO-1 expression because of Bach1-ablation and the subsequent antioxidant effects are crucial in imparting a protective effect against osteoarthritis." (PMID 36139853, 2022). "Thus, Bach1 ablation has beneficial effects against cardiovascular dysfunction, hepatotoxicity, intestinal toxicity, and osteoarthritis via the modulation of redox homeostasis." (PMID 36139853, 2022).
pancreatic ductal adenocarcinoma (4 papers, 2020 to 2022). An infiltrating adenocarcinoma that arises from the epithelial cells of the pancreas. "Mutation in BTB and CNC homology 1 (BACH1) has been associated with pancreatic ductal adenocarcinoma (PDAC) risk." (PMID 33109073, 2020). "BACH1 also promotes the malignant properties of cancer cells, including metastasis in breast cancer, pancreatic ductal adenocarcinoma (PDAC) and lung cancer." (PMID 36009179, 2022). "BTB and CNC homology 1 (BACH1) represses the expression of genes involved in the metabolism of iron, heme and reactive oxygen species and promotes metastasis of various cancers including pancreatic ductal adenocarcinoma (PDAC)." (PMID 36009179, 2022).
renal carcinoma (4 papers, 2016 to 2023). A carcinoma arising from the epithelium of the renal parenchyma or the renal pelvis. "Previously, the upregulation of BACH1 has been found to be associated with worsening prognoses in both lung and renal cancers." (PMID 37239002, 2023). "It is reported that miR-155-5p silencing inhibits proliferation and migration by upregulating BACH1 in renal cancer cells." (PMID 32587662, 2020). "Some of the predicted functions of miR-155-5p include the inhibition of proliferation, migration and induction of apoptosis by upregulating BACH1 in renal cancer cells." (PMID 29534467, 2018). "Li found that miR-155 exerted suppressive functions in proliferation and induced apoptosis by upregulating BACH1 in renal cancer cells." (PMID 26967247, 2016).
Sepsis (4 papers, 2022 to 2025). Sepsis is defined as life-threatening organ dysfunction caused by a dysregulated host response to infection. "Although Bach1 ablation after CLP-sepsis preserved mitochondrial bioenergetics, the RNA-seq analysis failed to observe the upregulation of genes that encode proteins modulate mitochondrial bioenergetics in the Bach1 knockout mice." (PMID 36139853, 2022). "In sepsis‐induced cardiac injuries, FTO inhibited ferroptosis to relieve heart inflammation and dysfunction in mice by regulating BACH1 expression." (PMID 39739936, 2025). "The boxplot revealed 26 differentially expressed genes between the sepsis-induced ALI and control samples: Ncf2, Slc2a6, Cd44, Txnip, Slc2a1, Ubc, Hspb1, Zfp36, Arntl, Ddit4, Tnfaip3, Txnrd1, Mt1, Hmox1, Gch1, Gclc, Stat3, Egfr, Hif1a, Bach1, Socs1, Dusp1, Cdkn1a, Fth1, Steap3, and Alox12." (PMID 37081490, 2023). "Besides attenuating tissue inflammation, the absence of Bach1 reduced mitochondrial dysfunction after CLP-sepsis by preserving bioenergetics function in mitochondria isolated from the liver of CLP-sepsis-induced mice." (PMID 36139853, 2022).
acute kidney injury (3 papers, 2017 to 2026). Sudden and sustained deterioration of the kidney function characterized by decreased glomerular filtration rate, increased serum creatinine or oliguria. "In a rat model of rhabdomyolysis-associated acute kidney injury (RM-AKI), after glycerol injection, Bach1 mRNA levels sharply increased at 3 h and remained elevated for 12 h." (PMID 41602837, 2026).